MUC5AC (mucin 5AC, oligomeric mucus/gel-forming)
Diseases named in the same sentence as MUC5AC in open-access papers (continued):
Sharing a sentence is not in itself a finding about the gene and the disease.
tumor (continued). "In addition, trichrome staining data also revealed that tumor matrix was reduced in A549 ST6GalNAc-I KO–derived (P = 0.002) and A549 MUC5AC KD–derived tumor xenograft tissues (P = 0.0008) compared with their respective controls." (PMID 40371640, 2025). "MUC5AC is involved in tumor angiogenesis and metastasis in various models." (PMID 40371640, 2025). "Moreover, in our study, MUC5AC was also proved to be related with other clinicopathological characteristics such as depth of tumor invasion, WHO grade, TNM, lymph metastasis, and lymphatic invasion." (PMID 39886661, 2024). "MUC5AC expression is linked to the serrated neoplasia pathway, characterized by CpG island methylator phenotype (CIMP) positivity, BRAF p.V600E mutations, mismatch repair deficiency, and advanced tumor stage." (PMID 39682117, 2024). "Additionally, treatment of tumor cells with an astrocyte-conditioned medium or the chemokine CCL2 resulted in upregulation of MUC5AC expression and enhanced brain colonization." (PMID 38825648, 2024). "Except for prognostic value, MUC5AC could also shape microbial networks in the tumor microenvironment of GC, predicting disease outcome." (PMID 39886661, 2024). "Moreover, the immunohistochemical staining test for tumor area was positive for MUC5AC and MUC6, also its pattern was different from that of normal duodenal mucosa." (PMID 36781821, 2023). "We noted an increased tumor mutation burden and a higher frequency of specific known driver mutations when compared to The Cancer Genome Atlas database; we also found novel mutations in MUC3A, MUC5AC, HCAR3, ORT2B, and PABPC." (PMID 36382570, 2023). "Being consistent, here we confirmed that MUC5AC acts as a tumor promoter." (PMID 37324942, 2023). "Regarding tumor stage, cases with advanced depth of invasion (pT4) demonstrated a tendency towards a loss of MUC5AC and CDX2 but not MUC2." (PMID 37240039, 2023). "Similarly, the immunohistochemical analysis of PCa tumor tissues suggests that MUC5AC is overexpressed in the recurrent adenocarcinomas." (PMID 36980526, 2023). "We anticipated that MUC5AC may act as a barrier against chemotherapy in human CRC tumours, and as a consequence, it could represent a prognostic biomarker for CRC." (PMID 35131032, 2022). "Importantly, both CMS1 (associated with immune evasion) and CMS3 (metabolic dysregulation and goblet cell markers enrichment) have worse prognosis than CMS2, which include the majority of tumours with low MUC5AC expression." (PMID 35131032, 2022). "Notably, S100P + cells accounted for 91.14% of total tumor cells from these seven iCCAs and displayed more representative and extensive-expression compared with the other markers (MUC5AC: 42.37%, and MUC6: 22.97%)." (PMID 35347134, 2022). "MUC5AC protein expression correlated with aggressive tumor features (e.g., distant metastases (p = 0.0334), BRAF mutation (p < 0.0001), mismatch repair-deficiency (p < 0.0001), and unfavorable 5-year overall survival (44% versus 65% for positive/negative staining)." (PMID 34475526, 2022). "The authors hypothesized that cancer-specific MUC5AC from the tumor cell lines in the supernatant fluid competes with NPC-1C Mab." (PMID 34205412, 2021). "Results revealed that the primary tumor had increased diffuse expression of MUC5AC and MUC6." (PMID 34264404, 2021). "In this study, we found that two non-intestinal markers, i.e. CK7 and MUC5AC, were expressed at significantly higher percentages in both tumour tissue and associated mucosa of CrD-SBC cases compared to ordinary no-PID-SBC cases." (PMID 33963925, 2021). "Tumor types that are always MUC5AC negative are of diagnostic interest, because a positive MUC5AC immunostaining will virtually exclude such entities from diagnostic considerations." (PMID 34547930, 2021). "Additionally, MUC5AC is linked to poor prognosis and would be a prospective therapeutic target in lung ADC due to its role in enhancing tumor heterogeneity with mucin production." (PMID 34976811, 2021).
tumor (continued). "In addition, our multivariate analyses showed that firstly MUC5AC expression and tumor localization independently predicted dMMR status and secondly dMMR status and tumor localization independently predicted MUC5AC expression status." (PMID 33373033, 2021). "At least weak MUC5AC positivity was seen in 44 of 111 (40%) tumor entities." (PMID 34547930, 2021). "Furthermore, the expression of MUC5AC decreases along with the local invasion of the tumor and with the increase in the number of lymph nodes with metastasis." (PMID 33322136, 2020). "We found that MUC5AC exhibited prominent immunoreactivity in the tumor cells of cervical AEC." (PMID 32843061, 2020). "Similarly, our orthotopic mouse model showed that the presence of MUC5AC enhanced tumor growth and metastasis, as corroborated in previous findings." (PMID 32098629, 2020). "The expression of MUC5AC was correlated with the degree of tumor differentiation (p = 0.036)." (PMID 32843061, 2020). "MUC5AC was found to suppress tumor secretion of the neutrophil attractant IL8 and, moreover, MUC5AC blocked TRAIL-R mediated apoptosis of tumor cells via an as yet unknown mechanism." (PMID 31333662, 2019). "Moreover, the tumor showed positivity for MUC5AC, indicating its differentiation into gastric foveolar epithelium." (PMID 30212986, 2018). "The surface layer of the tumor was immunohistochemically positive for MUC5AC." (PMID 28376132, 2017). "MUC5AC expression correlated with tumor location and mucinous subtype." (PMID 27298226, 2016). "Of note, the extent of MUC5AC expression was found to be related to disease outcome, that is, only 20 % of patients with high (>50 % of tumor cells) MUC5AC expression experienced disease progression, compared with 42 % of patients with low or absent MUC5AC expression (p = 0.055)." (PMID 27298226, 2016). "In BTC, recent studies from east Asia suggest that MUC4, as well as MUC5AC, may be suitable candidate tumour markers." (PMID 18475301, 2008). "Here, we evaluated the tumor morphology and immunohistochemical expression of CDH17 and CLDN18 in 25 CD-SBNs and potential relationships with gastric differentiation as indicated by MUC5AC and MUC6 immunohistochemistry, wnt pathway mutations, and mismatch repair gene protein immunohistochemistry." (PMID 39164422, 2025). "In addition to serving as a protective layer and barrier, there are reports that MUC5AC could inhibit the release of tumor cells, thereby reducing invasion and metastasis." (PMID 39886661, 2024). "Therefore, several groups used or developed anti-MUC5AC mAbs for therapy or tumour detection." (PMID 35892707, 2022). "Therefore, the current study aims to evaluate and compare the potential of tumor-associated glycans Lea/c/x, sdi-Lea, sLea, sLex and sTn, and mucins MUC1 and MUC5AC for molecular imaging of PDAC using a semi-automated, machine learning-based digital image analysis workflow." (PMID 34830932, 2021). "Additionally, MUC5AC was found to positively be expressed in the cases of Hp-induced, metaplastic, and atrophic hyperplasia of gastric epithelial cells while negatively expressed in cases of low-grade and high-grade neoplasia of epithelial cells." (PMID 33777138, 2021). "Apart from revealing the inhibitory effects of BR/NAC on tumor growth, this animal study also indicated, consistent with our in vitro observations, that BR/NAC therapy remarkably diminished the tumor production of the membrane-associated mucin MUC1, as well as of the secreted mucins MUC2 and MUC5AC." (PMID 26436698, 2015). "Overall, our studies demonstrated that ST6GalNAc-I–induced tumor cell sialylation through NECTIN2 and MUC5AC contributes to immune evasion and tumor angiogenesis." (PMID 40371640, 2025).
tumor (continued). "MUC5AC interacts with NECTIN2 to influence T-cell function and tumor angiogenesis, thereby promoting tumor immune evasion." (PMID 40655139, 2025). "Immunohistochemical analysis showed positivity for Mucin 5AC (MUC5AC) and MUC6, classifying the tumor as a gastric-type IPMN." (PMID 41181742, 2025). "First, we ranked the stemness of different tumor cell subtypes using the CytoTRACE method, and the observations supported that C1 NDUFAB1+ subtype possessed increased stemness properties, while C0 MUC5AC+ subtype exhibited lower stemness." (PMID 40688093, 2025). "In specific, study reported that tumor cells showed expression levels of MUC1 (77%), MUC2 (2%), MUC5B (63%), MUC5AC (36%) and MUC6 (21%)." (PMID 40655139, 2025). "In this study, we studied the role of ST6GalNAc-I in the modulation of NECTIN2/MUC5AC/VCAN for immune evasion and tumor angiogenesis during LUAD development." (PMID 40371640, 2025). "Expression of secreted mucins MUC2, MUC5AC, and MUC6 was detected in the cytoplasm (94%, 59% and 12% of all tumours, respectively)." (PMID 39966658, 2025). "Immunohistochemically, mucin 5AC (MUC5AC) and MUC6 were expressed in the tumor cytoplasm, classifying it as the gastric type." (PMID 41181742, 2025). "For example, mucin 5AC (MUC5AC) was identified in PDAC, indicating its role in promoting tumor progression." (PMID 40619414, 2025). "Mechanistically, ST6GalNAc-I/MUC5AC regulates VCAN-V1, a key factor in tumor matrix remodeling during angiogenesis and metastasis." (PMID 40371640, 2025). "One of the recommended approaches is the combination of CA 19-9 with other commonly used tumor markers, including CEA, CA 125, and CA 242, as well as novel markers such as macrophage inhibitory cytokine-1, mucin 5AC (MUC5AC)." (PMID 40723883, 2025). "High tumour staining for each of HMGA2, MUC5AC/6, IDH1, PIWIL2, DNA index, and RPL34 was significantly associated with poorer OS upon multivariable analysis." (PMID 38398089, 2024). "Immunohistochemically, the tumor cells are usually positive for CK7, CEA, MUC2, and MUC5AC and rarely positive for CDX2." (PMID 38672619, 2024). "Several promising molecular markers with prognostic significance were also identified, including tumour HMGA2, MUC5AC/6, IDH1, PIWIL2, and DNA index." (PMID 38398089, 2024). "A recent study showed the overexpression of MUC1, MUC19, MUC4, MUC5AC, and MUC5B in the mucinous metaplasia of tissues isolated from Pten conditional knockout mice and human PCa tumor tissues." (PMID 36980526, 2023). "Overall, mRNA expression of MUC1, MUC5AC, and MUC6 was significantly higher in the paired adjacent non-tumor tissues compared to the tumor and FD tissues." (PMID 37085819, 2023). "Immunohistochemical results of the perihilar tumor showed MUC1 (2 +), MUC2 (-) and MUC5AC (3 +), and the BilIN lesions exhibited MUC1 (-)." (PMID 37721561, 2023). "Subcluster 5, distinctly derived from the tumour tissue, overexpressed mucus secretion‐related genes (CXCL17, TFF3, MUC5AC, SPINK4 and MSMB, etc.)." (PMID 35075805, 2022). "Immunohistochemically, tumor cells show diffuse positivity for MUC6, while MUC2-positive goblet cells or MUC5AC-positive gastric foveolar metaplastic cells are observable, but are usually scattered." (PMID 35204432, 2022). "MUC5AC was found to be a significant determinant of a poor prognosis, especially in KRAS-mutant tumours." (PMID 36059804, 2022). "In this study, we aimed to validate the group of reported candidate-CCA biomarkers, namely S100A9, MUC5AC, TGF-β1, angiopoietin-2, and the commonly used tumor marker, CA19-9, in the sera of CCA patients compared with healthy people and other GI cancer groups." (PMID 33806004, 2021). "To further investigate the histopathological feature of tumor organoids and how this relates to parental tissues, we performed immunohistochemistry for pancreatic markers KRT7, MUC1 and MUC5AC, and the intestinal markers KRT20 and MUC2." (PMID 33327494, 2020).
tumor (continued). "Using the presence of expression in more than 10% tumour cells as cut-off for all 3 stains (MUC2, MUC5AC, AB/PAS), 670 (53%) cancers were classified as ‘triple negative’." (PMID 32488651, 2020). "Descriptions of some of the clinical cases indicate coexistence of strong MUC5AC-positivity in perihilar CCs and extensive MUC6-positivity in C-P neoplasm of PBGs, suggesting different origin of these neoplasms." (PMID 30875782, 2019). "Human serrated morphology CRCs and mouse Cdx2−/− BrafV600E-mutant tumor epithelium aberrantly expressed a number of gastric epithelial markers, including ANXA10, MUC5AC, and PDX1." (PMID 28072391, 2017). "Each of these was detected in control antrum and, with the exception of Muc5ac, were also highly expressed in some of the hyperplastic GLI2A-negative gastric epithelia within tumor masses (yellow asterisks)." (PMID 26859571, 2016). "These tumours are positive for cytokeratin 7 (CK7) with focal expression of carcinoembryonic monoclonal antibody (CEA-M), CA19-9, MUC1, B72.3, and MUC5AC." (PMID 26421012, 2015). "For sig-type GC, both the tumor lesion and background mucosa mostly showed strong expression of CTSE and MUC5AC, whereas expression of MUC2 was very weak in both of them." (PMID 23451082, 2013). "For pap-type GC, expressions of CTSE, MUC5AC, and MUC2 were considerably strong in both the tumor lesion and surrounding mucosa, which are quite different from the expression patterns of tub1/tub2-type GC." (PMID 23451082, 2013). "Immunohistochemically, as in the present case, the tumour typically expresses MUC6 and variably MUC5AC." (PMID 23206236, 2012). "We examined histological phenotype of tumors of AFPC or NEC containing the composite tumor by evaluating immunohistochemical expressions of MUC2, MUC5AC, MUC6, CDX2, and SOX2." (PMID 22482081, 2012). "Six of these non-previously reported variations were encountered in more than one tumor sample, and were confined to three genes, one in SATB1, four in MUC5AC and one in DDX26B." (PMID 21698250, 2011). "Additionally, the MUC5AC and FGFR2 protein expression levels were positively correlated in the tumor tissues." (PMID 41467942, 2025). "Further, co-occurrence of MUC5AC/CD31 or VCAN-V1/CD31 was drastically decreased in MUC5AC KD–derived (quantification) or ST6GalNAc-I KO–derived tumor xenograft tissues." (PMID 40371640, 2025). "On immunohistochemical analysis, the tumor was positive for MUC5AC and MUC6 and negative for MUC2 and CDX2, indicating a gastric phenotype." (PMID 41256328, 2025). "The tumor cells showed positive expression of MUC-6, CAIX, MUC5AC, HNF-1β, MUC-1, CK7, and Pax-8." (PMID 40018404, 2025). "Similarly, enriched coexpression of MUC5AC/CD31 and CD31/VCAN-V1 in human and mouse LUAD tissues suggests that MUC5AC/VCAN-V1 plays a critical role in tumor angiogenesis." (PMID 40371640, 2025). "Immunohistochemical staining revealed that the tumor cells were positive for MUC5AC and MUC6 and negative for Pepsinogen I and H + /K + -ATPase." (PMID 38583117, 2024). "MUC5AC is known to activate EMT and transwell migration in various types of tumor cells." (PMID 38825648, 2024). "We designed this retrospective study to demonstrate profiles of MUC expression (MUC1, MUC2, MUC5AC, and MUC6) of different histologic patterns within the same tumor among pulmonary adenocarcinomas and investigate correlations of MUC expression with clinicopathologic features." (PMID 36367122, 2023).
tumor (continued). "We observed that the expression of MUC5AC was absent in ductal cells from normal samples but enriched in part ductal cells from tumour samples, while FOSL2 was up-regulated in ductal cells from tumour samples compared to ductal cells from normal samples." (PMID 37380804, 2023). "With this aim, we designed this retrospective study to demonstrate profiles of MUC expression (MUC1, MUC2, MUC5AC, and MUC6) of different histologic patterns within the same tumor among pulmonary adenocarcinomas and investigate correlations of MUC expression with clinicopathologic features." (PMID 36367122, 2023). "In contrast, MUC2 for goblet cells was negative, and MUC5AC for foveolar cells was stained in the non-atypical foveolar epithelium that was covered on the tumor surface." (PMID 35029193, 2022). "In another study, CMS classification was associated with mucin-to-tumor area quantification, and revealed that CMS2 CRC had no mucin and MUC5AC protein expression was an indication for worse overall survival." (PMID 35453885, 2022). "Tumor immunohistochemical analyses were presented as follows: Inhibin-α (-), ER (-), Vimentin (mesenchyme +), CK7 (+), CK19 (+), CK20 (−), CEA (−), MUC-1 (+), MUC-5AC (+), MUC-6 (+), MUC-2 (−), S-100p (focal+), and Ki-67 (12% +)." (PMID 33592896, 2021). "Four cases were covered with non-neoplastic foveolar epithelium on the tumor and the deeper area of the lesion was composed of various tumor cells (MUC5AC-positive) (the ‘non-exposure type’, Type 3)." (PMID 34268625, 2021). "Hence, classical PDAC typically consists of (low grade) well-differentiated tumor tissues, which frequently express (>10%) mucin markers associated with pancreatic differentiation, together with the O-linked glycosylated MUC5AC and MUC1 mucins, but not MUC2 or MUC6." (PMID 34503261, 2021). "In the present analysis, 67 of 111 (60%) analyzed tumor types and subtypes did never show MUC5AC immunostaining." (PMID 34547930, 2021). "We observed that MUC5AC was overexpressed in CRC patients and cancer cell lines, and its knockdown in CRC cell lines reduced proliferation, invasion, and migratory potential, suggesting that MUC5AC has a tumor promoting role in CRC." (PMID 32098629, 2020). "Muc5AC is a protein that stimulates angiogenesis in PDAC and might also suppress the immune response towards the tumor." (PMID 32886718, 2020). "We observed high MUC2 expression (a marker of intestinal type gastric cancer) in JSC15-3 cells and high MUC5AC and MUC6 expression (markers of stomach type gastric cancer) in JSC17-7 cells, which are consistent with differentiation status of original tumour tissues." (PMID 31607750, 2019). "A tumor with exclusive expression of CA19-9 in moderately-differentiated PDAC with no surrounding stroma expressed neither β-catenin nor MUC5AC, but a moderately-differentiated PDAC secreting primarily sTRA expressed both." (PMID 28642461, 2017). "Additional staining of full-blown tumors for markers expressed in normal antral glands revealed that GLI2A-expressing tumor cells did not express Muc5ac or Tff2, and infrequently stained with the mucin-binding lectins GSII and UEA1." (PMID 26859571, 2016). "Different cell populations in normal stomach express Muc5ac and bind GSII lectin but these markers were co-localized in cells from rapamycin-treated mice, suggesting that some tumor cells activate an aberrant differentiation program when mTOR signaling is inhibited." (PMID 26859571, 2016). "Immunohistochemical analyses revealed a similar expression and distribution patterns of CDX2 (nuclear), CK20 (cytoplasmic), E‐Cadherin (membrane), MUC2 (extracellular,; intracellular signet ring PMP) and MUC5AC (extra‐ and intracellular, and Z') in PMP PDX tumor as in human tumors." (PMID 26833741, 2016).